MERTK (MER proto-oncogene, tyrosine kinase)
Diseases named in the same sentence as MERTK in open-access papers (continued):
Sharing a sentence is not in itself a finding about the gene and the disease.
atherosclerosis (continued). "The effects of MerTK in atherosclerosis progression to date has been investigated in phagocytic immune cells—primarily macrophages." (PMID 30980657, 2019). "Inactivation of the MERTK protein in atherosclerotic plaques via proteolytic cleavage impairs macrophage efferocytosis and promotes necrosis, defective resolution and progression of atherosclerosis." (PMID 40068774, 2025). "The mechanism studies showed that the miR-218–5p/ECMerTK/MAPK axis may play an important role in endothelial MerTK-mediated atherosclerosis." (PMID 40953531, 2025). "In addition, we identify signaling pathways of endothelial dysfunction, SMC phenotypic alterations, and mitochondrial dysfunction as the key drivers in endothelial MerTK-mediated atherosclerosis." (PMID 40953531, 2025). "The RNA-seq big data analytics and BioGPS data emphasized endothelial MerTK may play a novel role in atherosclerosis." (PMID 40953531, 2025). "The recent studies showing that targeted delivery of the MerTK protein in macrophages improves efferocytosis and reduces atherosclerosis in diabetic ApoE−/− mice and the aPC mediated restoration of MerTK in the current study supports the translational relevance of the current study." (PMID 41083981, 2025). "Consequently, in our study of endothelial MerTK-mediated atherosclerosis, NADPH oxidase activation was utilized as an indirect indicator of mitochondrial function." (PMID 40953531, 2025). "The axis of miR-218-5p/ECMerTK/MAPK plays a key role in endothelial MerTK-mediated atherosclerosis." (PMID 40953531, 2025). "Our findings demonstrate that endothelial MerTK deficiency activates both NADPH oxidases and MAPK family kinases (ERK, p38 MAPK and JNK), supporting the key role of endothelial MerTK in the development of atherosclerosis." (PMID 40953531, 2025). "Previous studies of efferocytosis in atherosclerosis mainly focused on MerTK in macrophages." (PMID 40953531, 2025). "Our in vivo data of proteomics and immunostaining showed that, compared with WT group, MerTK-/- aggravates atherosclerosis in d-flow areas through upregulation of endothelial dysfunction markers (e.g. IL-1β, NF-κB, TLR4, MAPK signaling, vWF, VCAM-1 and p22phox) and mitochondrial dysfunction." (PMID 38646649, 2024). "Our study indicates that MerTK decrease in macrophages contributes to the aggravated atherosclerosis in diabetic ApoE–/– mice and regional restoration of MerTK in macrophages of the plaque via HMNVs could be a promising therapeutic approach." (PMID 38614985, 2024). "Interestingly, MerTK-/-induces obvious abnormal endothelial thickening accompanied with decreased endothelial efferocytosis, promoting the development of atherosclerosis." (PMID 38646649, 2024). "Our investigation indicates that decrease of MerTK plays a crucial role in atherosclerosis in diabetic mice, and restoration of MerTK could mitigate atheroslcerosis potentially through promoting efferocytosis." (PMID 38614985, 2024). "Therapeutic approaches that increase MERTK or TREM2 could promote plaque stabilization in inflammasome-driven atherosclerosis." (PMID 39531316, 2024). "The goals of the present study were to assess atherogenesis in a hyperlipidemic, LAB model of Jak2VF, then to define the mechanisms of accelerated atherosclerosis, especially those involving IL-1β–mediated crosstalk from mutant to WT myeloid cells that led to reduced levels of MERTK and TREM2." (PMID 39531316, 2024). "This study was designed to investigate whether endothelial MerTK and EC efferocytosis respond to blood flow patterns during atherosclerosis." (PMID 38646649, 2024). "Although only aortic ECs are directly exposed to wall shear stress in the physiological conditions compared with macrophages and SMCs, it cannot differentiate which cell-expressed MerTK plays the most important role in d-flow-mediated atherosclerosis with MerTK-/- mice." (PMID 38646649, 2024).
atherosclerosis (continued). "The role of MerTK in d-flow-mediated endothelial dysfunction and its implications for the pathological process of atherosclerosis, is also unknown." (PMID 38646649, 2024). "In atherosclerosis, effective efferocytosis in the early stages contributes to inflammation resolution, but in the advanced stage, reducing oxLDLs and inhibiting cleavage of MERTK can suppress the impairment of efferocytosis." (PMID 32346605, 2020). "MERTK-/- and LXRs DKO mice share a series of features, including amplified pro-inflammatory responses and increased susceptibility to both autoimmunity and atherosclerosis." (PMID 31191323, 2019). "AXL, a member of the TAM (Tyro3, Axl, MerTK) family of receptors, plays important roles in cell survival, clearance of dead cells (efferocytosis), and suppression of inflammation, which are processes that critically influence atherosclerosis progression." (PMID 27958361, 2016). "Using MerTK gene global knockout mice (MerTK−/−) with partial carotid ligation (PCL) surgery to establish acute disturbed flow-induced atherosclerosis model, we reported that endothelial MerTK is sensitive to disturbed flow and may play a key role in the development of atherosclerosis." (PMID 40953531, 2025). "For example, MerTK inhibition emerges as a new strategy for cancer therapy due to it counteracts effect on anti-tumor immunity, while MerTK restoration represents a promising treatment for atherosclerosis and myocardial infarction as MerTK is cleaved in these disease conditions." (PMID 38341954, 2024). "Therefore, MerTK, by maintaining the integrity of the endothelial barrier, may in principle also contribute to impeding the development of atherosclerosis; however, further work needs to be done to explore this aspect." (PMID 30980657, 2019). "In addition, if the TAM receptor ligand Protein S were particularly important in advanced atherosclerosis, the finding that Protein S has a greater affinity for MerTK versus Axl may help explain the dominance of MerTK in this setting." (PMID 27958361, 2016). "TNFα and IL-1β, which are abundant in advanced atherosclerosis, can promote ADAM17-dependent proteolytic cleavage of MerTK, substantially disabling efferocytosis​." (PMID 40172727, 2025). "MerTK is the main receptor for efferocytosis and plays an important role in cardiovascular disease (CVD) including atherosclerosis, myocardial infarction and hypertension." (PMID 40953531, 2025). "However, the specific role of endothelial MerTK in the pathogenesis of atherosclerosis is unknown." (PMID 40953531, 2025). "Our findings also show the feasibility for the setup acute atherosclerosis model combining with PCL-induced d-flow, AAV8-PCSK9 and MerTK gene knockout." (PMID 38646649, 2024). "Phagocytic receptors such as MERTK and TREM2 are thought to have an important role in the resolution of inflammatory processes in atherosclerosis." (PMID 39531316, 2024). "Although MerTK cleavage is a causal mechanism in driving plaque necrosis in advanced atherosclerosis, the pathophysiologically relevant inducers of MerTK cleavage in the context of atherosclerosis were not known." (PMID 41031413, 2025). "Our study not only unravels that diabetes aggravates atherosclerosis at least partially via decreasing MerTK expression and thus efferocytosis in macrophages, but also indicates that the HMNV-based MerTK delivery could be a promising therapeutic approach." (PMID 38614985, 2024). "Therapeutic approaches that stabilize MERTK or TREM2 could promote plaque stabilization, especially in CH- and inflammasome-driven atherosclerosis." (PMID 39531316, 2024).
atherosclerosis (continued). "More MerTK will enhance the efferocytosis and thus be beneficial in the context of atherosclerosis, either with or without diabetes." (PMID 38614985, 2024). "Similarly, LRP1, progressively downregulated during atherosclerosis, can also be rendered inactive through ADAM17-mediated proteolytic cleavage akin to MerTK." (PMID 39660125, 2024). "Our data showing that Axl deficiency in bone marrow-derived cells does not affect the most important parameters of advanced atherosclerosis is quite surprising and cannot be explained by compensatory up-regulation of MerTK or Tyro3." (PMID 27958361, 2016). "On the other hand, treatments apt to elicit the expansion of MerTK+ and CD163+ cells (e.g., M2c polarizing agents and IL-4/STAT-6 inhibitors) may help against atherosclerosis progression." (PMID 25972766, 2015). "The second major finding revealed that efferocytosis might occur efficiently during early atherosclerosis but not in advanced atherosclerosis due to significant expression of MerTK in the least coronary obstructive patients." (PMID 33761885, 2021).
retinitis pigmentosa (38 papers, 2009 to 2025). Retinitis pigmentosa (RP) is an inherited retinal dystrophy leading to progressive loss of the photoreceptors and retinal pigment epithelium and resulting in blindness usually after several decades. "The importance of MerTK in phagocytosis is evident since inherited inactivating variants of MerTK are found in individuals suffering from retinitis pigmentosa." (PMID 39663766, 2025). "MerTK has been extensively researched in the context of retinal pigment epithelium and macrophages, where its mutations are linked to severe retinitis pigmentosa and the dysregulation of macrophage functions in phagocytosis and inflammation." (PMID 39845889, 2024). "In retinitis pigmentosa, the implicated genes that appeared across multiple studies include MERTK, PDE6B, CERKL, and ABCA4." (PMID 36836473, 2023). "Mutations in MERTK have been associated with retinitis pigmentosa and early onset retinal dystrophies." (PMID 36848389, 2023). "Retinitis pigmentosa is caused by multiple molecular interactions, of which the phagocytic dysfunction induced by a MERTK mutation in RPE cells is one of the most vital." (PMID 35492354, 2022). "The Royal College of Surgeons rat model of retinal degeneration has been linked to loss-of-function of MERTK, and together with the MERTK knock-out mouse, phenocopy retinitis pigmentosa in humans with MERTK mutations." (PMID 34973110, 2022). "Internalization is stimulated by MerTK, a step essential for phagocytosis; hence, mutations inactivating MerTK lead to retinitis pigmentosa, an inherited form of retinal degeneration." (PMID 36121394, 2022). "Previous researches utilizing MER proto-oncogene tyrosine kinase (MERTK) gene therapy in Royal College of Surgeons (RCS) rats evidenced its effectiveness in treating MERTK-associated retinitis pigmentosa (RP)." (PMID 34970569, 2021). "We used RCS rats as a retinitis pigmentosa model, which show progressive photoreceptor degeneration as the consequence of MERTK mutation in the RPE cells." (PMID 34948073, 2021). "MerTK mutations cause severe forms of retinitis pigmentosa with childhood onset and complete blindness in early adulthood." (PMID 34440696, 2021). "In a 29 year-old woman with retinitis pigmentosa, WES identified an apparently homozygous splice site variant in MERTK associated with retinitis pigmentosa (MIM #613862)." (PMID 30557390, 2018). "Ingestion of the outer segments is regulated through Mer Tyrosine Kinase (MERTK); mutations in this gene are responsible for defects in phagocytosis and the onset of retinitis pigmentosa in humans and retinal dystrophy in the RCS rat." (PMID 19204785, 2009). "Mutations in the MerTK gene have been shown to disrupt retinal pigment epithelial phagocytosis in rats and mice, and result in retinitis pigmentosa in patients." (PMID 19028587, 2009). "Given the comparable expression of MERTK in the RPE of mouse, rat and human, together with the translation of a loss-of-function MERTK genotype to a retinitis pigmentosa clinical phenotype, the weight of evidence suggests significant utility of a mouse model in translation to the clinic." (PMID 34973110, 2022). "Indeed, expression of phosphomimetic Dbl3 in retinitis pigmentosa iPSC-derived MerTK-deficient RPE cells rescued phagocytosis, indicating that it represents the main phagocytic effector pathway downstream of MerTK." (PMID 36121394, 2022). "Recently, we reported the generation of a hiPSC model of MERTK-associated Retinitis Pigmentosa (RP) that recapitulates disease phenotype and the subsequent creation of gene-corrected RP-hiPSCs using Clustered Regularly Interspaced Short Palindromic Repeats (CRISPR)/Cas9." (PMID 33672445, 2021). "In addition to retinitis pigmentosa, genetic associations of MERTK have also been reported in a few other traits." (PMID 32492107, 2020). "Bi-allelic pathogenic variants in MERTK cause retinitis pigmentosa (RP)." (PMID 33353011, 2020).
retinitis pigmentosa (continued). "Indeed, AAV-mediated correction of retinitis pigmentosa (RP) due to mutations in MERTK (RP38), which like RPE65 is expressed in the RPE, has also been relied to the clinic after extensive pre-clinical studies." (PMID 31238338, 2019). "Following this, and the identification of mutations in humans with retinitis pigmentosa where loss of MERTK function has also been demonstrated, its biology has been widely investigated due to the potential of gene therapy to correct deficiencies in MERTK expression caused by mutations in the gene." (PMID 28813472, 2017). "Indeed, dysfunctional phagocytosis has been described in both acquired age-related macular degeneration (AMD) and genetically inherited retinal degenerative diseases, including retinitis pigmentosa (RP) caused by mutations in Mer receptor tyrosine kinase (MERTK) and bestrophinopathies." (PMID 33242397, 2020). "Identifying the primary and secondary cell types and stimulus mechanism for such inflammatory pathways will be a subject of future studies and may identify cellular molecular targets for therapies aiming to delay onset of the aggressive forms of retinitis pigmentosa associated with defective MerTK." (PMID 32765507, 2020). "The rescue of MERTK expression in retinitis pigmentosa (RP38) patient RPE counteracted these defects." (PMID 34207717, 2021). "Studies on mutant MerTK expression or function in retinitis pigmentosa patients have yet to be reported." (PMID 34440696, 2021). "These cells were then reprogrammed to iPSC and differentiated into mature RPE cells with an aim to characterise this iPSC derived model of MERTK retinitis pigmentosa, and employ TRIDs to restore MERTK function." (PMID 28246391, 2017). "Mutations in MERTK, which underlie the dystrophic phenotype observed in the RCS rat and some human forms of retinitis pigmentosa, revealed the importance of this protein in the maintenance of a healthy retina." (PMID 19204785, 2009). "Only about 15% of total MERTK transcripts are mis-spliced, making it unlikely to be a disease-causative mutation for retinitis pigmentosa, the rare disease typically associated with the gene, especially given its high frequency in the African population." (PMID 35743704, 2022). "Our proteomic data showed significant changes in the levels of proteins for retinitis pigmentosa (RPE65, RP2, MERTK, and RBP3), X-linked retinoschisis (RS1), CRB1-retinal dystrophy (CRB1), Usher syndrome (PCDH15), and Leber congenital amaurosis (RD3 and KCNJ13)." (PMID 36139394, 2022). "Patients from three families with a phenotype of EoHM and retinal dystrophy had variants in KCNV2 (OFT-00092), MERTK (OFT-00474) and ARL6 (OFT-00407), genes with a phenotype of retinal cone dystrophy in the case of KCNV2 and retinitis pigmentosa in the other two cases." (PMID 35457050, 2022). "Additionally, RM rescued POS internalization defect in Mer receptor tyrosine kinase (MERTK) mutant hRPE, derived from retinitis pigmentosa patient induced pluripotent stem cells." (PMID 33242397, 2020). "MERTK deficiency results in a form of retinitis pigmentosa, RP38, a rod cone dystrophy for which there is no effective treatment." (PMID 28246391, 2017). "PTC124 (10 μg/mL) was shown to restore the expression of MERTK protein and RPE phagocytic activity (12% of control RPE level), which suggests that ataluren can be used to treat retinitis pigmentosa due to nonsense variants in MERTK, which has no effective therapies so far." (PMID 34451881, 2021). "Evaluating the effectiveness of transplantation can lay the foundation for the development of new treatments for these diseases, including retinitis pigmentosa with RPE-related gene abnormalities (such as RPE65, RDH5, and MERTK), AMD with RPE atrophy." (PMID 33923985, 2021). "Consistently, POS ensheathment, fragmentation, and internalization were abolished in MERTK mutant RPE, and rescue of MERTK expression in retinitis pigmentosa (RP38) patient RPE counteracted these defects." (PMID 32160519, 2020).
retinitis pigmentosa (continued). "MerTK is known for its role in retinal pigment epithelium (RPE), mediating rapid phagocytosis and clearance of photoreceptor debris, with its dysfunction leading to retinal dystrophy and retinitis pigmentosa." (PMID 39845889, 2024). "MerTK-independent activation of MRCKβ signaling by a phosphomimetic Dbl3 mutant rescues phagocytosis in retinitis pigmentosa RPE cells lacking functional MerTK." (PMID 36121394, 2022). "MERTK was not previously known to be associated with AS or AAU, whereas mutations in MERTK gene lead to an inherited retinal disorder, named retinitis pigmentosa." (PMID 32492107, 2020).